FOXO3 (forkhead box O3)
Diseases named in the same sentence as FOXO3 in open-access papers (continued):
Sharing a sentence is not in itself a finding about the gene and the disease.
cancer (continued). "The previous studies have shown that miR-498 could target FOXO3 (forkhead box O3) and hTERT (human telomerase reverse transcriptase) to inhibit cancer cell proliferation." (PMID 29970131, 2018). "Here, we prove the feasibility of assigning genes to cancer pathways by genome-wide forward genetics using genome-edited human cell systems, link FOXO3, NCOA3, and TCF7L2 to phenotypes of the EGFR/Ras/MAPK pathway, and implicate FOXO3 and NCOA3 in the response to anti-EGFR therapy." (PMID 29301589, 2018). "The contrasting roles of FOXO3 in the maintenance of CSC properties documented may suggest that FOXO3 may have different functions in CSCs of different cancer types." (PMID 29180117, 2018). "As FOXO3 is a crucial regulator of apoptosis induced by various stress stimuli or anti-cancer drugs, we next examined whether FOXO3 is required for siREP1-mediated apoptosis under serum-starved conditions and 5-FU treatment." (PMID 28055019, 2017). "We propose that in cancer cachexia, increased FoxO3 occupancy at pro-atrophic genes MuRF1, MAFbx/Atrogin-1, and GABARAPL1 is promoted by AMPK-mediated FoxO3 phosphorylation, which is ultimately induced by increased systemic IL6 levels and AMPK activation in skeletal muscle." (PMID 29167426, 2017). "The PTEN/FOXO3/AKT axis is a main regulator of the fate in cancer cells." (PMID 28729699, 2017). "May be the dysregulation of circ-Foxo3 is relevant to the neuromuscular degenerative diseases or even the germination of cancer." (PMID 28279183, 2017). "Since c-Myc, KLF5, and DRD2 have been suggested to increase cancer stem cell-like populations in various tumors, reducing these proteins in response to BPD and TFP suggests a novel FOXO3-dependent mechanism underlying BPD- and TFP-induced apoptosis in TNBC cells." (PMID 27283899, 2016). "Therefore, we proposed that ergosterol peroxide treatment induced cancer cell death via enhancing the activation of Foxo3 by repressing c-Myc to promote pro-apoptotic genes Bax and Puma expression." (PMID 27058618, 2016). "Forkhead box O3A (FOXO3a) is an important transcription factor involved in various human cancers." (PMID 27127880, 2016). "It has already become apparent that FoxO3 plays in important role in disease progression in age‐related diseases, such as cancer, and may be useful for monitoring responses to treatment." (PMID 27071935, 2016). "Foxo3 deregulation is essential in the development of cancer." (PMID 26098777, 2015). "Dissection of the target genes of Foxo1 and Foxo3 under DR conditions might reveal precise pathways that regulate cancer and aging in mammals." (PMID 25808402, 2015). "This study examined the role of Foxo3 in lifespan extension and cancer suppression in DR mice." (PMID 25808402, 2015). "FOXO3 overexpression in cancer cells could be related to nutrient deprivation stress and other stimulatory factors that lead to autophagy induction." (PMID 24527027, 2014). "To test this, we introduced a FOXO3-targeting siRNA into cancer cells and examined whether downregulating FOXO3 affects RRM2B levels." (PMID 24947616, 2014). "In addition, decreased levels of Sp1 in the late stages of cancer increased the expression of FOXO3 and N-cadherin, leading to cancer metastasis." (PMID 24519909, 2014).
cancer (continued). "Paradoxically, cytostatic and cytotoxic effects of a diverse spectrum of anti-cancer drugs, such as paclitaxel, doxorubicin, lapatinib, gefitinib, imatinib, and cisplatin, are mediated through the FoxO3 activation and/or the inhibition of its direct target FOXM1." (PMID 25566078, 2014). "Mammalian FoxO3 is similar to yeast Hcm1 and is involved in cell cycle, aging and cancer." (PMID 23874301, 2013). "We sought to investigate the crosstalk of different PTMs on the FoxO3 which leads to the onset/progression of various cancers and that could also potentially be targeted as a therapeutic point of intervention." (PMID 22489133, 2012). "Consequently, the down-regulation of circ-Foxo3 impedes cancer cell apoptosis." (PMID 39944836, 2025). "Moreover, restoring or stabilizing the transcriptional–electrical program pharmacologically (e.g., through SKCa/IKCa activators or FOXO3-inducing agents) may offer therapeutic potential in cardiovascular disease, cancer, or tissue repair." (PMID 41262983, 2025). "In addition, FOXO3 is known to be involved in a variety of diseases, including cancer and diabetes." (PMID 39334758, 2024). "Therefore, understanding the mechanisms by which FOXO3 exerts its anti-cancer effects may have implications for the development of targeted therapies in cancer treatment." (PMID 39334758, 2024). "In addition, FOXO3 maintains dormant stemness and suppresses cancer stem cells." (PMID 38612866, 2024). "We found similarities in pathways and upstream regulators of FOXO3-deficient macrophages with HFD obese mice colon associated with inflammation (IL-1A, IL-1B, IL-6, IL-8 signaling), growth (ILK signaling, CDK5 signaling, VEGF signaling) and cancer (cAMP-mediated signaling)." (PMID 35323693, 2022). "Furthermore, the correlation of miR-155 and FOXO3 was previously reported in tumors as follows: expression of miR-155 is upregulated in tumors and acts as an oncogene in cancer, while expression of FOXO3 is downregulated and can inhibit the development of tumors." (PMID 35664920, 2022). "Notably, CircFOXO3 via sponging of miR-138-5p and miR-432-5p could increase proliferation and invasion of GBM cells in vitro and in vivovivo, which shows the high value of FOXO3 gene and their subordinates in cancers." (PMID 36132137, 2022). "Moreover, FOXO3 is closely related to stem cell-like properties in various cancers." (PMID 34795388, 2022). "Therefore, it is crucial to investigate the role of FOXO3 in various cancer cells." (PMID 35207737, 2022). "While FOXO3 is not primarily known as a major cancer predisposition gene, it is considered to be a tumour suppressor due to its role in regulating the immune system, inflammation, and oxidative stress, as well as cell proliferation, DNA damage, metabolism, and apoptosis." (PMID 34943892, 2021). "Hence, L-carnitine ameliorated cancer cachexia via the Akt/FOXO3/MaFbx and p70S6K pathways." (PMID 34724970, 2021). "Alterations in DNA methylation at the FOXO3 gene could therefore represent an additional, non-genetic mechanism affecting gene expression and causing cancer and premature death." (PMID 34943892, 2021). "Indeed, recent research has shown that PERK (PKR-like endoplasmic reticulum kinase, also called eukaryotic translation initiation factor 2-alpha kinase 3 (EIF2A3K)) is regulated by FOXO3 and thus exposed a transformed cell and chemotherapeutic drug–resistant cancer cell vulnerability in PERK." (PMID 32372224, 2020). "This suggests that Foxo3 may be an important target in drug screening for cancer intervention." (PMID 27058618, 2016). "We further showed that ergosterol prolonged animal survival by up-regulating Foxo3 and Foxo3 downstream molecules Bim, Fas, and Fas L. These results provide new insight for future development of Amauroderma rude as an effective and safe medical mushroom for use by cancer patients." (PMID 26098777, 2015).
cancer (continued). "However, it remains largely unknown how FOXO3 regulates the activation of caspase-3 protein in cancer cells in response to auranofin treatment." (PMID 25096914, 2014). "Moreover, Overexpression of RRM2B and/or FOXO3 inhibited the proliferation of cancer cells." (PMID 24947616, 2014). "This homeostatic maintenance, induced by the regulation of the FOXO-3 protein, highlights the importance of SIRT1 for aging and cancer." (PMID 39858038, 2025). "At present, in the research on cell cycle inhibition of tumors and cancer cells, it has been found that FSH induced phosphorylation of FOXO3/4 and played a role in this process." (PMID 40428322, 2025). "NRF2 not only promotes the expression of antioxidant proteins such as forkhead box protein O3 (FOXO3), but also maintains the stemness of cancer cells by upregulating transcription factors such as Notch, Hedgehog, and β-catenin." (PMID 38704599, 2024). "In overrepresentation analysis in the current study, common mRNA targets of miR-197 included IL-8, FOXO3, and mitogen activated protein kinase 1 (MAPK1), which map to pathways related to cancer, inflammation/immunity, and cellular activity." (PMID 39359416, 2024). "Further, individually “M” has been proven to bring about 5′adenosine monophosphate-activated protein kinase (AMPK) mediated inhibition of fork-head box O3 (FOXO3) and AKT in various cancers." (PMID 37025487, 2023). "While, the expression levels of PDCD4 and FOXO3 were significantly upregulated in both cell types treated with Car-NIO, Mel-NIO, and olaparib in comparison with untreated cancer cells." (PMID 37808196, 2023). "miRNA-183 targets programmed cell death 4 (PDCD4) and Fork-head box O3 (FOXO3) to increase proliferation and invasion in human carcinoma." (PMID 37808196, 2023). "Decreased expression FOXO3 and increased expression of FOXM1, which contribute to increased chemoresistance in cancer has been reversed in co-treatments (5FU+UroA or 5FU+UAS03) suggesting potential translational applications." (PMID 35910798, 2022). "Mechanically, 6,7-dimethoxycoumarin upregulates the expression of FOXO3 and p27, thereby inhibiting the phosphorylation of CDK4/6 and exerting its inhibitory effect on cancer cell proliferation." (PMID 35607323, 2022). "Both FOXO3 and FOXO4 were shown to be involved in maintaining the self-renewal capacity of HSCs and cancer stem cells." (PMID 35406686, 2022). "FOXO3, a member of the FOX transcription factor family, is frequently described as being deregulated in cancer." (PMID 36727057, 2022). "Among them, FOXO3 was upregulated in HCC cells subjected to Met treatment and enriched for transcriptional misregulation in cancer." (PMID 34546972, 2021). "Transcription factors, such as FOXO3 and TFEB, have also been shown to take their part in autophagy regulation in dormant cancer cells, as in ESCs." (PMID 34832087, 2021). "The regulation of FOXO3 by miR-155 was related to oral cancer, HCC, nasopharyngeal cancer and many other cancers." (PMID 34150756, 2021). "Forkhead box O3 (FOXO3), a central factor expressed by hepatocytes, has been related to cancer progression." (PMID 34771514, 2021). "Consistent with the primary cancer, PDX tissues were classified into 3 types based on the FOXO3 expression patterns: FOXO3-negative (20.0%), FOXO3-Nuc (26.7%), and FOXO3-Cyt (53.3%)." (PMID 33795838, 2021).
cancer (continued). "In contrast, PPP2R2A was the most deleted gene found in > 20% of samples across 17 cancers, followed by the deletion of SLC2A4 in 16 cancers and five additional genes (FOXO3, PPP2CB, PPP2R2D, PPP2R5C and PPP2R5E) in 15 cancer types." (PMID 32807122, 2020). "Specifically, high FOXO1 and FOXO3 expression has been correlated with matrix metalloproteinase (MMP) upregulation and enhanced cancer metastasis." (PMID 32372224, 2020). "In cancer cells, FANCD2 also interacts with FOXO3 to regulate antioxidant gene expression in response to oxidative stress." (PMID 32372224, 2020). "Therefore, FOXO3 may be an important therapeutic target of various cancers." (PMID 33312341, 2020). "In support of this mechanism, van der Vos and colleagues showed that in cancer cells under nutrient starvation, transcriptional induction of GS1 by FOXO3 resulted in autophagy and survival with the concomitant inhibition of the TOR pathway." (PMID 31941072, 2020). "circ-Foxo3 also protects Foxo3 from ubiquitination and deterioration in an MDM2-dependant manner, thus promoting apoptosis in cancer cell lines." (PMID 32781555, 2020). "Clearly, future more in-depth studies are needed to define the clinical applications of FOXO3 inhibition by CBX in high-stage NB, in other “FOXO-resistant” cancers, or even in neurodegenerative diseases." (PMID 31591479, 2020). "Here, we identify the ER-stress modulator PERK as a direct downstream target of FOXO3 and explore the regulation of PERK expression by FOXO3 as a vulnerability in drug-resistant cancer cells." (PMID 31312024, 2019). "FOXO3 and FOXM1 are members of the forkhead box transcription factor family which play opposite roles in tumorigenesis, drug resistance and cancer progression." (PMID 31727006, 2019). "Accordingly, dysregulation of FOXO3 and/or FOXM1 is responsible for the acquisition of multi-drug resistance in cancer cells." (PMID 29180117, 2018). "Previous studies have also reported that FOXO3 can antagonize the functions of FOXM1, which contributes to cancer initiation, progression, and drug resistance." (PMID 30514328, 2018). "Our results confirmed that the interaction of p-FoxO3 with the 14-3-3 protein determined by an immunoprecipitation assay was increased in the CGCA group, compared with the cancer alone and CGC groups." (PMID 29731967, 2018). "Phosphorylation of FOXO3 on Ser7 by the MAPK14 MAP kinase has been shown to promote its nuclear localization in response to doxorubicin, an anti-cancer drug that induces cytotoxicity by stimulating the production of intracellular free radicals." (PMID 27532863, 2016). "This resembles the heterogeneity of NB tumors in vivo and suggests that cultured patient-derived cancer cells reflect the stage-dependent differences in PKB-activity and FOXO3-phosphorylation observed in tissue biopsies." (PMID 27769056, 2016). "Unexpectedly, we uncover that both TFP and BPD display suppression of the expression of the dopamine receptor D2 (DRD2), which has been suggested as a key receptor for selective-targeting cancer stem cells (CSC), in a FOXO3-dependent manner." (PMID 27283899, 2016). "miR-221/222, which is frequently upregulated in cancer, targets Bim, PTEN and FoxO3, thus fortifying apoptotic resistance." (PMID 26405162, 2015). "Among these candidates, six genes (RhoGDI1, ALCAM, FOXJ2, FOXO3, NDRG2 and SOX11) were involved in the suppression of cancer metastasis." (PMID 26460549, 2015).
cancer (continued). "In accordance with these results, we observed that when FOXO3 was overexpressed, RRM2B was induced and the proliferation of cancer cells was inhibited (Figure 4biii)." (PMID 24947616, 2014). "In accordance with these findings, the current results indicate that FOXO3 can activate and regulate RRM2B and inhibit the growth of cancer cells." (PMID 24947616, 2014). "Using filtering for genes involved in stem cell pluripotency, drug resistance, signal transduction and cancer, a few genes recurrently affected by genomic variations were identified, including TNFSF10 and FOXO3." (PMID 25593988, 2014). "We obtained results indicating that patients expressing high/high FOXO3/RRM2B levels exhibited superior outcomes regarding the death rate and cancer recurrence or metastasis rate, compared with that of the patients in the low/low group." (PMID 24947616, 2014). "FOXO3 overexpression correlated with expression of the Gabarapl1, ATG12, PIK3C3, LC3, and Beclin1 genes in cancer tissues." (PMID 24527027, 2014). "Mechanistically, METTL3 deletion decreases the transcription efficiency of Forkhead box O3 (FOXO3) via a YTHDF1-dependent fashion and thereby promotes autophagy, a crucial process in multidrug resistance in chemotherapy of cancer, thus ultimately resulting in sorafenib resistance." (PMID 38545555, 2024). "Additionally, it has been reported that MUL1 levels are regulated by the transcription factor FOXO3, another member of FOXO family, in cancer cells and primary myotubes." (PMID 37051468, 2023). "However, the biological effects of FoxO3 K270 and K271 methylation by SET7/9 need to be investigated in order to unravel the role of SET7/9-FoxO3 axis in cancer development." (PMID 35069908, 2022). "In the context of DNA damage, FOXO3 deacetylation‐mediated apoptosis is also attenuated, suggesting that SIRT1‐mediated deacetylation of FOXO proteins significantly reduces apoptosis in cancer cells." (PMID 34866322, 2022). "Here, we evaluated the expression, prognostic value, mutation, methylation, and clinical features of four FOXO family genes (FOXO1, FOXO3, FOXO4, and FOXO6) in 33 types of cancers based on the Cancer Genome Atlas (TCGA) and Genotype Tissue Expression (GTEx) databases." (PMID 36555288, 2022). "By integrating patterns of FOX genes expression with anticancer drugs sensitivity, we speculated that six FOX genes, including FOXO3, FOXO1, FOXN3, FOXK2, FOXN2, and FOXJ3, might be important for the development and treatment of a wide range of cancers." (PMID 36292640, 2022). "Finally, APDT led to up-regulation of developmental transcription factors involved in stem cells and cancer stem cells (ETV4, SOX9, FOXO1 and FOXO3)." (PMID 35328625, 2022). "In present study, we reported that IFITM3 served as a novel modulator of HGF/MET-mediated AKT signaling that suppressed FOXO3 (Forkhead Box O3), consequently leading to c-MYC (MYC proto-oncogene) mediated cancer proliferation, migration, stemness and drug resistance." (PMID 35941699, 2022). "Moreover, CSNK2A1 renders cancer cells resistant to apoptotic stresses by activating BCL2 and suppressing PML, FOXO3, and PARP1." (PMID 34359939, 2021). "FOXO3 could respond to hypoxic stress and block HIF1-mediated apoptosis by regulating CITED2 in cancer cells, and HIF-1 related hypoxia pathways were acknowledged as working in RCC." (PMID 34461918, 2021).